LRRC25 (leucine rich repeat containing 25)
Description:
Plays a role in the inhibition of RLR-mediated type I interferon signaling pathway by targeting RIGI for autophagic degradation. Interacts specifically with ISG15-associated RIGI to promote interaction between RIGI and the autophagic cargo receptor p62/SQSTM1 to mediate RIGI degradation via selective autophagy. Also plays a role in the inhibition of NF-kappa-B signaling pathway and inflammatory response by promoting the degradation of p65/RELA.
Synonyms: MAPA; FLJ38116
Tractability: Antibody: UniProt predicts a signal peptide or a membrane-spanning region. PROTAC: its protein half-life has been measured.
Gene: Protein-coding gene on chromosome 19 (18,391,137 to 18,397,622, reverse strand). Ensembl gene ENSG00000175489.
Subcellular location: Membrane; Cytoplasm
Subcellular location (Human Protein Atlas): Cytosol; Endoplasmic reticulum; Microtubules
Gene Ontology:
Molecular function: protein binding
Cellular component: cytoplasm; cytosol; membrane
Genetic constraint (gnomAD): Loss-of-function variants: 6 observed, 20.93 expected, observed/expected ratio (o/e) 0.29, 90% interval 0.16 to 0.57. The upper end of that interval is the gene's LOEUF score, 0.57, which puts it in group 2 of 6, group 1 being the genes least tolerant of losing a copy. Missense variants: 341 observed, 410.81 expected, observed/expected ratio (o/e) 0.83, 90% interval 0.76 to 0.91. Synonymous variants: 161 observed, 185.99 expected, observed/expected ratio (o/e) 0.87, 90% interval 0.76 to 0.99.
Homologues: Orthologues: chimpanzee LRRC25 (98% identical), macaque LRRC25 (89% identical), pig LRRC25 (61% identical), dog LRRC25 (57% identical), rat Lrrc25 (50% identical), mouse Lrrc25 (48% identical).
Diseases named in the same sentence as LRRC25 in open-access papers:
LRRC25 is named in the same sentence as 35 diseases in open-access papers, as found by Europe PMC text mining. Sharing a sentence is not in itself a finding about the gene and the disease. The quoted sentences say what the papers report.
breast carcinoma (5 papers, 2017 to 2024). "A prior study also reported that the expression of LRRC25 was significantly associated with the risk of developing breast cancer." (PMID 38476461, 2024). "Of note, RCCD1 and LRRC25 were identified as likely targets of known breast cancer risk variants in our analysis." (PMID 30988301, 2019). "In a study of the cis-eQTL activity of known cancer loci, the 19p13.11 breast cancer risk SNP rs4808801 was most significantly associated with the expression of LRRC25 (p-value: 3.2 x 10-03)." (PMID 28362817, 2017). "Out of 33 LRRC25 whole blood eQTL SNPs, five showed evidence of an association with breast cancer risk." (PMID 28362817, 2017). "Furthermore, we found that higher expression levels of ACAP1 (p-value: 1.9x10-05) and LRRC25 (p-value: 5.2x10-05) were suggestively associated with an increased risk of breast cancer." (PMID 28362817, 2017). "If LRRC25 overexpression results in an elevated inflammatory response, then it could also increase the risk of breast cancer." (PMID 28362817, 2017). "Also suggestively associated with breast cancer risk, albeit contributing less than 0.1% of the weight for predicting LRRC25 expression, was rs3795026 (p-value: 0.013)." (PMID 28362817, 2017). "The next two strongest signals were for SNPs in moderate LD with rs11668719, namely rs7257932 (r2 = 0.39; p-value: 2.5x10-04), which is the only SNP predicting LRRC25 expression previously implicated in breast cancer GWAS, and rs13344313 (r2 = 0.43; p-value: 3.2x10-03)." (PMID 28362817, 2017). "Neither ACAP1 nor LRRC25 have previously been implicated by GWAS of breast cancer risk." (PMID 28362817, 2017).
Alzheimer disease (3 papers, 2023 to 2024). A progressive, neurodegenerative disease characterized by loss of function and death of nerve cells in several areas of the brain leading to loss of cognitive function such as memory and language. "The expression of LRRC25 in microglial cells is reduced in Alzheimer’s disease patients carrying disease-associated SNVs." (PMID 38542318, 2024). "Studies have identified LRRC25 as a potential risk gene for Alzheimer’s disease (AD) by sequencing the transcriptome of microglia and analyzing chromatin accessibility." (PMID 37894158, 2023). "A recent study suggested LRRC25 is a potential risk factor for Alzheimer’s disease (AD)." (PMID 38476461, 2024). "Lower expression levels of LRRC25 may inhibit autophagy, hindering cells from eliminating misfolded proteins and aggregates, such as amyloids typical of Alzheimer’s disease." (PMID 38542318, 2024).
glioma (3 papers, 2020 to 2024). A benign or malignant brain and spinal cord tumor that arises from glial cells (astrocytes, oligodendrocytes, ependymal cells). "On the contrary, LRRC25 levels are decreased in primary lower-grade glioma and many other tumor cell lines at both mRNA and protein levels, and therefore may be protective against tumors." (PMID 38476461, 2024). "Additionally, LRRC25 was confirmed to play a protective role in primary lower-grade glioma, and was shown to be significantly upregulated during neonatal hypoxic-ischemia neuronal damage in vitro." (PMID 38476461, 2024). "Further investigations are warranted to explore the mechanisms of LRRC25 in glioma." (PMID 32431729, 2020). "Among them, ARHGDIB, LRRC25, PLAUR, and TREM1 were selected as prognostic hub genes in lower grade glioma in previous bioinformatic analyses." (PMID 34858984, 2021). "The mRNA expression of APOBEC3C, FCGRT, GNG5, and SP100 was elevated in glioma, whereas the expression of ADAP2, ALOX5AP, and LRRC25 was low." (PMID 32431729, 2020).
viral infection (2 papers, 2023 to 2024). "Functionally, LRRC25 is implicated in regulating autophagy during viral infection and has been shown to promote the degradation of RIG-1 and p65/RelA thereby negatively regulating the signaling pathways of NF-κB, and interferon and thus suppress the production of inflammatory cytokines." (PMID 38476461, 2024). "It is important to note that the anti-inflammatory role of LRRC25 has been demonstrated in response to viral infections." (PMID 38476461, 2024). "The role of LRRC25 has been extensively studied in viral infection." (PMID 37894158, 2023). "Furthermore, the construction of an LRRC25 knock-down cell line significantly enhanced the cell’s ability to combat virus infection." (PMID 37894158, 2023). "Increasing evidence suggests that LRRC25 plays a crucial negative role in downregulating the inflammatory response caused by virus infection." (PMID 37894158, 2023).
acute myeloid leukemia (1 paper, 2024). Acute myeloid leukemia (AML) is a group of neoplasms arising from precursor cells committed to the myeloid cell-line differentiation. "Furthermore, a study focusing on acute myeloid leukemia (AML) has indicated that, in AML patients, there is a significant decrease in the proportion of monocytes, while LRRC25 exhibits high expression in primary bone marrow cells (granulocytes and monocytes) but low expression in lymphocytes." (PMID 39544234, 2024).
autoimmune disease (1 paper, 2023). A disorder resulting from loss of function or tissue destruction of an organ or multiple organs, arising from humoral or cellular immune responses of the individual to their own tissue constituents. "It is also known that the expression of LRRC25 is regulated by vitamin D, which reduces the progression of autoimmune diseases." (PMID 37511476, 2023).
cardiac hypertrophy (1 paper, 2022). "Similar results were shown in LRRC25-knockout mice; an LRRC25 deficiency significantly accelerates pathological cardiac hypertrophy in mice by increasing the NF-κB and TGF-β1 activation signaling pathway to increase inflammation." (PMID 36440001, 2022).
Cerebral ischemia (1 paper, 2024). Restriction of arterial blood supply to the brain associated with insufficient oxygenation to support the metabolic requirements of the tissue. "Increased LRRC25 expression in the cell model of cerebral ischemia has been shown to have a specific effect on this disease that is known to contribute to cognitive deficits." (PMID 38542318, 2024).
Cognitive impairment (1 paper, 2024). Abnormal cognition is characterized by deficits in thinking, reasoning, or remembering. "Based on the TWAS, the LRRC25 gene was the only gene that showed a statistically significant association with cognitive impairment." (PMID 38542318, 2024). "The most significant association was found between cognitive impairment and lower expression levels of LRRC25 (z-score = −4.118; p-value = 3.83 × 10−5)." (PMID 38542318, 2024). "An autophagy-related decrease in LRRC25 expression in the cerebral cortex may be associated with cognitive impairment." (PMID 38542318, 2024).
colorectal cancer (1 paper, 2025). A primary or metastatic malignant neoplasm that affects the colon or rectum. "LRRC25-mediated immune evasion may play a critical role in RIG-I-dependent cancers(e.g., melanoma, colorectal cancer, and non-small cell lung cancer), suggesting that combining LRRC25 inhibition with ICIs could enhance therapeutic outcomes in these contexts." (PMID 40517171, 2025).
coronary atherosclerosis (1 paper, 2025). Atherosclerosis of the coronary vasculature. "According to the authors, during the progression of human coronary atherosclerosis there is a dynamic disruption of the autophagy landscape, which could be protected by the lncRNA LUCAT1/hsa-miR-6776-5p/LRRC25-driven mechanism of autophagy activation." (PMID 40283676, 2025).
COVID-19 (1 paper, 2023). A disease caused by infection with severe acute respiratory syndrome coronavirus 2. "Simultaneously, the upregulation of LRRC25, which is a potent negative regulator of NF-κB signaling and inflammation, may counteract the hyper-inflammation state in patients with COVID-19." (PMID 37047248, 2023). "Notably, the elevated plasma level of LRRC25 detected in patients with COVID-19 has not previously been reported." (PMID 37047248, 2023).
gastric cancer (1 paper, 2025). A primary or metastatic malignant neoplasm involving the stomach. "Similarly, high expression of LRRC25 in gastric cancer has been reported to create an immunosuppressive microenvironment by modulating chemokine axes." (PMID 41458604, 2025).
hypoxic-ischemic encephalopathy (1 paper, 2024). "In this context, it should be noted that oxygen-glucose-deprived human fetal cortical neurons also showed increased LRRC25 mRNA and may suggest a crucial role in the pathogenesis of hypoxic-ischemic encephalopathy." (PMID 38476461, 2024).
myeloid leukemia (1 paper, 2018). A clonal proliferation of myeloid cells and their precursors in the bone marrow, peripheral blood, and spleen. "Western blots confirmed that LRRC25 is down-regulated in myeloid leukemia cells while highly expressed in granulocytes and monocytes, and up-regulated after induction to granulocytes in HL60, NB4, and APL bone marrow cells at the protein level." (PMID 28536942, 2018). "LRRC25 was undetectable/poorly expressed in myeloid leukemia cell lines, including U937, K562, MEG-01, NB4, HL60, and THP-1 cells, while it was highly expressed in mature myeloid cells, such as granulocytes and monocytes." (PMID 28536942, 2018). "Initially, we investigated whether ectopic LRRC25 affected proliferation and promoted spontaneous differentiation of myeloid leukemia cells." (PMID 28536942, 2018). "To further explore the expression of LRRC25 in primary myeloid leukemia cells, we collected samples of bone marrow cells (27 normal and 32 AML) and detected the expression of LRRC25 by real-time PCR." (PMID 28536942, 2018).
periodontitis (1 paper, 2024). An acute or chronic inflammatory process that affects the tissues that surround and support the teeth. "In our study, LRRC25 was the only gene that exhibited causal association with both T2D and periodontitis, which had the potential to mitigate the risk of the two diseases." (PMID 39544234, 2024). "Based on existing research, we speculate that the mechanisms by which LRRC25 reduces the risk of T2D and periodontitis may be intricately linked to the inhibition of inflammatory responses." (PMID 39544234, 2024). "For patients with both T2D and periodontitis, we believe that LRRC25 will be a reliable therapeutic target, and more drugs targeting LRRC25 will be developed in the future." (PMID 39544234, 2024). "In patients with periodontitis and patients with T2D and periodontitis, we observed that LRRC25+ IM exhibited normal intercellular communications with other cell clusters, mainly through LGALS9 associated signaling pathways." (PMID 39544234, 2024). "It should be noted that LRRC25 was identified as protective genes for both T2D (OR = 0.96, 95% CI: 0.93-0.99, p = 3.44 ×10−2) and periodontitis (OR = 0.92, 95% CI: 0.84-0.99, p = 4.45 ×10−2)." (PMID 39544234, 2024). "Thirdly, Due to the lack of data on periodontitis, we did not verify the causal relationship between LRRC25 and periodontitis." (PMID 39544234, 2024). "Consequently, we identified NCF1 as core therapeutic targets for T2D and LRRC25 for T2D and periodontitis." (PMID 39544234, 2024). "Finally, we identified NCF1 as the core therapeutic target for T2D (OR = 1.09, 95% CI: 1.03-1.14, p = 1.85 ×10−3) and LRRC25 for T2D (OR = 0.96, 95% CI: 0.93-0.99, p = 3.44 ×10−2) and periodontitis (OR = 0.92, 95% CI: 0.84-0.99, p = 4.45 ×10−2)." (PMID 39544234, 2024).
psoriasis (1 paper, 2023). An autoimmune condition characterized by red, well-delineated plaques with silvery scales that are usually on the extensor surfaces and scalp. "In this study, we identified three novel genes associated with psoriasis after the conditional and joint analysis: LRRC25, SSBP4, and ELL." (PMID 37511476, 2023). "We also identified five novel psoriasis risk genes, methionine sulfoxide reductase A, elongation factor for RNA polymerase II (ELL), Myotubularin Related Protein 9 (MTMR9), leucine-rich repeat containing 25 (LRRC25), and single-stranded-DNA-binding protein 4 (SSBP4), among 26 genes." (PMID 37511476, 2023). "Because psoriasis patients in previous studies tended to have low vitamin D levels, increasing vitamin D levels through consumption or synthesis by appropriate sun exposure may promote the expression of LRRC25 and alleviate inflammatory responses." (PMID 37511476, 2023).
tuberculosis (1 paper, 2023). A chronic, recurrent infection caused by the bacterium Mycobacterium tuberculosis. "To investigate the relationship between LRRC25 and the anti-tuberculosis immunity of microglia, we used siRNA to interfere with the expression of LRRC25." (PMID 37894158, 2023). "The present study showed that LRRC25 negatively regulates the anti-tuberculosis immunity of microglia, and one possible mechanism is the activation of the type I IFN pathway when Mtb or its bacterial components, such as EC, penetrate the blood–brain barrier and reach the microglia." (PMID 37894158, 2023). "Next, we attempted to determine whether LRRC25 could inhibit the release of ISG15 in the extracellular space by mediating the degradation of ISG15 and then inhibit the release of IFN-γ to negatively regulate the anti-tuberculosis immunity of BV2 cells." (PMID 37894158, 2023).
tuberculous meningitis (1 paper, 2023). "Double-labeled immunofluorescence analysis of IBA-1 and LRRC25 expression in mice with tuberculous meningitis showed a significant increase in LRRC25 expression compared to the control group." (PMID 37894158, 2023). "Furthermore, in the mouse model of tuberculous meningitis, LRRC25 expression was significantly upregulated, suggesting its involvement in the anti-Mtb immune response of microglia." (PMID 37894158, 2023). "Moreover, we observed a significant increase in LRRC25 expression in the brain region of mice with tuberculous meningitis at the animal level." (PMID 37894158, 2023). "Given the important role of microglia in neuroinflammation, the present study aimed to investigate the LRRC25 in Mtb-infected microglia of mice (BV2 cells) and provide insights into the pathogenesis and treatment of tuberculous meningitis." (PMID 37894158, 2023).
tumor (6 papers, 2016 to 2026). "In primary HGSOC, the recurrent tumor-specific DEG IL7R exhibited a positive correlation with AMBP and HDGF and a negative correlation with FEN1, LRRC25, RIGI, and TBL1X (p < 0.05)." (PMID 41596598, 2026).
infection (4 papers, 2018 to 2023). The state of being infected such as from the introduction of a foreign agent such as serum, vaccine, antigenic substance or organism. "Flow cytometry and laser confocal imaging were used to observe the infection of BV2 cells after LRRC25 silencing." (PMID 37894158, 2023). "ELISA analysis showed that IFN-γ and ISG15 levels in cell culture supernatant decreased after H37Rv infection, while they significantly increased after LRRC25 silencing." (PMID 37894158, 2023). "After 4 h of infection, the mRNA and protein levels of LRRC25 were assessed using Q-PCR and Western blotting." (PMID 37894158, 2023). "Overall, these findings indicate that LRRC25 exhibits increased expression at both the transcriptional and translational levels following H37Rv infection of BV2 cells." (PMID 37894158, 2023). "To further confirm whether the decrease in ISG15 and IFN-γ is caused by the activation of LRRC25, we quantified the mRNA of ISG15 in the four groups of cells before and after transfection and before and after infection." (PMID 37894158, 2023). "The expression levels of LRRC25 mRNA were then examined after 4 h of infection." (PMID 37894158, 2023). "By interfering with the expression of LRRC25 through siRNA transfection, the anti-infection ability of microglia against Mtb was significantly enhanced, highlighting the importance of LRRC25 as a molecule that negatively regulates the microglial susceptibility to Mtb." (PMID 37894158, 2023). "Given that LRRC25 is highly expressed in myeloid cells, it may be involved in immune responses such as infection and inflammation, in addition to myeloid cell development." (PMID 28536942, 2018). "To ensure that the decrease in the proportion of infected cells following LRRC25 knock-down was not due to cell death, we assessed cell viability before and after transfection and infection." (PMID 37894158, 2023). "Conversely, LRRC25 was not expressed in C8-D1A cells, and its expression in HT22 cells was low and downregulated after infection." (PMID 37894158, 2023).
bacterial infection (1 paper, 2023). "However, the role of LRRC25 in bacterial infection is still unclear." (PMID 37894158, 2023). "However, the role of LRRC25 in bacterial infection, particularly Mtb infection, has not been reported yet." (PMID 37894158, 2023).
LRRC25 also shares sentences with these, for which no sentence is quoted: cancer (5 papers); bladder cancer (1); campylobacteriosis (1); dementia (1); gastroesophageal reflux disease (1); infectious disease (1); inflammatory bowel disease (1); melanoma (1); neuritis (1); non-small cell lung carcinoma (1); schizophrenia (1); serous ovarian carcinoma (1); visceral leishmaniasis (1).